MUC4 (mucin 4, cell surface associated)
Diseases named in the same sentence as MUC4 in open-access papers (continued):
Sharing a sentence is not in itself a finding about the gene and the disease.
cancer (continued). "The MUC4-expressing cells also demonstrated an enhanced tumorigenicity in an orthotopic xenograft nude mice model, further supporting a direct role of MUC4 in inducing the cancer properties." (PMID 17595659, 2007). "MUC4 is a type-1 transmembrane glycoprotein and is overexpressed in many carcinomas." (PMID 17595659, 2007). "Similarly, some cancer studies have revealed a relationship between MUC4 and cell death." (PMID 38956298, 2024). "However, mutations in genes that are involved in immunoresistance of cancers such as ASXL, MUC4, MUC16 or MUC17 may negatively affect the efficacy." (PMID 36980598, 2023). "However, it is still ambiguous whether MUC4 can play a promoting or inhibiting effect across the cancer types, depending on the particular cancer and cell context." (PMID 36091120, 2022). "Interestingly, MUC4 was predictive of many cancer types when it had either non-silent mutations or synonymous mutations." (PMID 34385450, 2021). "However, it remains unclear whether MUC4 can be characterized as a friend or foe across the cancer types." (PMID 34336844, 2021). "The excessive expression of MUC4 in cancer tissue could reflect a dual role as an oncogene." (PMID 32701958, 2020). "Thus, TQ-induced TTP overexpression reduces target MUC4 expression and suggests that this reduction of the cancer gene, MUC4, may inhibit cancer cell proliferation and metastasis." (PMID 31141941, 2019). "Thus, TQ-induced TTP expression reduced the expression of the new target gene, MUC4, suggesting that such a decrease in MUC4 may inhibit cancer cell progression." (PMID 31141941, 2019). "However, in such forms of cancer, the presence of MUC4 indicates a more favorable prognosis." (PMID 27829225, 2017). "In addition, the MUC4-ErbB2-ERK pathway has been shown to contribute to the characteristic resistance of PDC to gemcitabine by inhibiting the activation of intrinsic apoptosis in cancer cells." (PMID 27829225, 2017). "Hence, it is no surprise that the increased expression of MUC4 is seen in several types of cancer and associates with poor prognosis." (PMID 28978023, 2017). "Thus, we have reviewed 19 articles of MUC4 IHC study applied for various human cancer tissues." (PMID 23152882, 2012). "Interestingly, we found downregulation of several components (integrins α1/α5/α6, epithelial-stromal interaction 1 (EPSTI1), fibronectin type III) that may, together with altered MUC4 expression in cancer cells, modify epithelial-stromal interactions." (PMID 22393391, 2012). "Alteration of mucin glycosylation is well-described in cancer and may modify MUC4 properties." (PMID 22393391, 2012). "Despite the fact that it is thought that MUC4 may alter migration/invasion/adherence properties of cancer cells via its huge extracellular domain and modified steric hindrance, adherence to two kinds of matrix was not modified in the absence of MUC4 in our model." (PMID 22393391, 2012). "The current chapter shows the importance of various mucins (MUC1, MUC3A, MUC4, MUC4β, MUC5AC, MUC5B, MUC7, and MUC16) and their mucin-bound carrier proteins in different cancers." (PMID 40699805, 2025). "MUC4 also increases the activity of EGFR family proteins, which in turn activate cancer cell proliferation, growth, motility, and invasion through actin filaments." (PMID 40655139, 2025). "MUC4, MUC1, and MUC16 are involved in the regional invasion and migration of cancer cells through various signaling pathways." (PMID 40699805, 2025). "Genes LGALS8, PDE4DIP, RAD17, ELN, MUC4 and SEMA4D had a mid-range expression in both cancer types, while OPRM1 and ADRA1 were the least expressed, thereby corroborating the results from our box plot and survival analysis." (PMID 38544823, 2024). "Epigenetic regulation of mucin expression, such as MUC1, MUC2, MUC4, MUC5AC and MUC17, has been reported to be controlled by DNA methylation in a variety of cancer cells." (PMID 36778111, 2023).
cancer (continued). "MUC1, MUC2, MUC4, MUC5AC, and MUC6 are currently the most widely covered in the literature regarding their role in the progression from normal colonic tissue to cancer." (PMID 36900282, 2023). "Given the proven significance of AS in cancer and the need for the identification of predictive biomarkers in CRC, we characterized the AS isoforms of MUC4 and ADAM12 in CRC." (PMID 36675796, 2023). "Pan-cancer driver genes with high alteration rates include FLNA (Filamin A, 41.86%), MUC4 (Mucin 4, 41.86%), and FAT3 (FAT Atypical Cadherin 3, 39.53%)." (PMID 36653483, 2023). "Similar to a previous ST study, we observed the high expression of mucin family genes in cancer cells, such as MUC16, MUC4, and MUC5B." (PMID 37124494, 2023). "More work is needed to determine whether Muc4 expression is the driver of pit cell metaplasia, or whether Muc4 may be a passenger in another gene expression program that drives disease development; indeed, metaplastic pit cells express other metaplasia- and cancer-related genes." (PMID 37674528, 2023). "Immunohistochemical analysis showed that 6 gene (NLRX1, AKT1, CSRP1, LEP, MUC4 and SEMA4B) of 10 genes were abnormal expressions between cancer and paracancer tissue." (PMID 36817485, 2023). "O-glycosylated MUC4, a glycoprotein overexpressed in pancreatic ductal adenocarcinoma (PDAC), potentiates malignancy properties in cancer cells." (PMID 35454762, 2022). "However, direct structure–function studies of MUC4 have been hampered by its large molecular size, lack of domain-specific reagents, and complexities associated with the existence of diverse glycoforms and splice variants in cancer." (PMID 34887447, 2021). "On the basis of the specific structure, MUC4 was suggested to modulate HER2/ERBB2 signaling and play a critical role in cancer." (PMID 34336844, 2021). "Of these, NCOR1, MUC4, and MUC16 genes have been investigated for their aberrant expression in various cancers and being attractive targets for immunotherapy in previous studies." (PMID 33504001, 2021). "Targeting the MUC4/HER2 complex has, thus, become a promising alternative route to target HER2 driven cancers." (PMID 34830899, 2021). "Four cancer‐driver genes NOTCH2, ASXL1, PDE4DIP, and MUC4 were found to be selectively amplified in both hESC‐RPE and HS980 (p38) samples." (PMID 32319201, 2020). "Some mucins have been used or proposed as biomarkers for carcinomas, such as MUC16 (CA125) and MUC4." (PMID 32175327, 2020). "For the 19 Mucin (MUC) family genes, nine of them were RMGs and four of them (MUC17, MUC5B, MUC4, and MUC16) were common RMGs shared in 8 to 17 cancer types." (PMID 30107644, 2018). "Ingenuity pathway analysis revealed that differentially methylated CpG sites were annotated to genes involved in ‘cell cycling’ (e.g. NDRG1, NEDD1, and MAD1L1), ‘inflammatory diseases’ (e.g. PRTN3), and ‘cancer’ (PCDHA6, MUC4, and ATP2C2)." (PMID 28754985, 2017). "Consistently, our results showed the simultaneous lack of NIDO, AMOP and vWD domains (NAV△) weakened the roles of MUC4/Y on malignant activities of PANC-1 cell in vitro, including cancer metastasis-related capabilities." (PMID 28060749, 2017). "It has been shown previously that expression of mucin genes (including MUC1, MUC2, MUC3, MUC4 and MUC5AC) is regulated by DNA methylation at promoter regions in cancer cell lines." (PMID 27283771, 2016). "Several mucin (MUC) glycoproteins have been shown to be overexpressed during cancer and have therefore been targeted in cancer vaccines, including MUC1, MUC4, MUC5AC, and MUC16." (PMID 26557640, 2015). "The expression rates in cancer lesions (more than 5% of carcinoma cells stained) were MUC1, 51.7% (31/60); MUC2, 26.7% (16/60); MUC3, 55% (33/60); MUC4, 51.7% (31/60); MUC5AC, 33.3% (20/60); MUC6, 10% (6/60) and MUC16, 8.3% (5/60)." (PMID 24722639, 2014).
cancer (continued). "For mucins with equal expression in SBC and normal tissue, MUC4 and MUC6 both showed cytoplasmic expression in carcinoma cells and normal epithelium (insets)." (PMID 24722639, 2014). "Six genes, including ADD3, CTNND1, EPB41L3, F3, MUC4 and PDGFA, showed cancer-tissue-specific DES events." (PMID 22905095, 2012). "MUC4 overexpression leads to increased (0.1%) side population (SP) and CD133-positive cancer stem cells compared to the control cells." (PMID 21521521, 2011). "MUC4 has been shown to act as an unorthodox ligand for ErBB2/HER2, potentiating its responsiveness in cancer signaling." (PMID 21521521, 2011). "Qverexpressed MUC4 and control cells were stained with FITC-conjugated CD133 cells to analyze the percentage of the cancer stem cell population." (PMID 21521521, 2011). "In our study we have also analyzed MUC4, HER2, ALDH1 and CD133 for the cancer stem cells and Shh for the self-renewal pathway in the isolated colonies from MUC4 overexpressed SKOV3 cells and SKOV3-MUC4." (PMID 21521521, 2011). "HER2 and cancer stem cell specific marker ALDH1 along with Shh, a self-renewal marker, showed increased expression in the isolated circular colonies compared to MUC4-transfected cells." (PMID 21521521, 2011). "This suggests that MUC4 stabilizes HER2 and enriches the cancer stem cell population, by either a direct or indirect mechanism which is yet to be explored." (PMID 21521521, 2011). "However, increased expression of EMMPRIN, VEGF, MUC-4, and E-cadherin in the intestinal component compared to the diffuse counterpart also provided evidence that the original carcinoma cells might undergo distinct carcinogenic routes resulting in the morphological distinction of both components." (PMID 18266006, 2008). "In addition to MUC4, Gal-3 is also a ligand for MUC1 in epithelial cells, which induces MUC1 cell surface polarization, increased cancer cell aggregation, and adhesion to vascular endothelium." (PMID 40699805, 2025). "However, dysregulation in mucin expressions, such as MUC1, MUC2, MUC4, MUC5AC, and MUC16, have been observed in many cancer cells." (PMID 40699805, 2025). "Moreover, MUC4 has distinct extracellular and cytoplasmic tail domains that work together to promote EGFR signaling, which is essential for cancer cell behaviors such as invasion and metastasis." (PMID 40655139, 2025). "Indeed, MUC4 activates Src/Focal adhesion kinase (FAK) and stabilization of HER2 and, thereby, promotes cancer cells survival, invasion, and metastasis." (PMID 40076457, 2025). "In addition, we observed the expression dysregulations of NLRX1, AKT1, CSRP1, LEP, MUC4 and SEMA4B in cancer tissues by immunohistochemistry." (PMID 36817485, 2023). "Samples consisted of 2-mm tissue cores from regions of superficial cancer, deep cancer, and non-neoplastic epithelium adjacent to cancer, which were immunostained for MUC4 and the proliferation marker Ki-67." (PMID 37674528, 2023). "For instance, PRDM16 functions as a tumor suppressor gene in malignant tumors, and the overexpression of PRDM16 could inhibit EMT by repressing MUC443,44, and MUC4 has been reported to be overexpressed in IMPC45, which is consistent with the losses of PRDM16." (PMID 35013309, 2022). "MUC4 expression is independent of mucus secretion in both normal human airways and carcinomas before epithelial differentiation." (PMID 36059804, 2022). "However, nothing is known at the molecular level about the way in which MUC4 and HER2 interact despite the fact that PPI networks play important roles in cellular function and biological processes such as cancer." (PMID 34830899, 2021). "MUC4 is a cell-surface membrane-bound glycoprotein that sterically masks cell surface antigens to protect cells from immune recognition—most notably in cancer cells —and a specific role in the placenta has not been well defined." (PMID 34299281, 2021).
cancer (continued). "Regarding MUC4 and MUC4/HER2 activation of downstream signaling pathways and their role in the biology of cancer, our studies highlight the importance of the regulation of key tumorigenic processes such as proliferation and migration, cell survival, and interaction with the micro-environment." (PMID 34830899, 2021). "Contrary to this knowledge surrounding mucins in the PMT, MUC-4, and MUC-1 have been shown to play a crucial role in the EMT, where these contribute to the malignant transformation, invasiveness and metastatic potential of cancer cells." (PMID 33193109, 2020). "The oncogenic potential of MUC4 is not surprising since silencing of MUC4 decreases the proliferation of many cancer cells." (PMID 33328627, 2020). "Similarly to MUC1 and MUC4, MUC16 overexpression in cancer promotes EMT, cell proliferation, migration and metastasis." (PMID 31514468, 2019). "We also observed a decrease in cancer invasion and migration from TQ treatment as well as a reduction in the expression of EMT-related genes, such as N-cadherin, TWIST, SLUG, SNAIL, ZEB1 and ZEB2, including downstream MUC4." (PMID 31141941, 2019). "We also analyzed MUC4, MUC16 and MUC20 expression in datasets of other cancers." (PMID 30236127, 2018). "It is interesting to note that MUC4 expression is not correlated with MUC1 that is a major membrane-bound mucin commonly overexpressed in cancer." (PMID 30236127, 2018). "Surprisingly, patients with MUC3A, MUC4, MUC5B, MUC6, and MUC16 mutations had significantly better OS prognoses compared with those without mutations in several cancer types." (PMID 30107644, 2018). "MUC4 plays a role in cell differentiation rather than cell proliferation of the normal goblet cells, the stratified squamous epithelial cells, and malignant epithelial tumor cells." (PMID 29317712, 2018). "The multiple functions of MUC4 originating from its abundant polymorphic capabilities, its glycosylation, the flexibility of its protein backbone structure, and the repeats in its VNTR region are among the primary influencers of cancer cell growth." (PMID 27829225, 2017). "Despite several studies on the oncogenic potential of MUC4 in various cancers, there is no detailed study on the expression of MUC4 in bladder pathology." (PMID 24671186, 2014). "In this study, we investigated the relationships between mucin expression and clinicopathologic factors in 60 SBC cases, in which expression profiles of MUC1, MUC2, MUC3, MUC4, MUC5AC, MUC6 and MUC16 in cancer and normal tissues were examined by immunohistochemistry." (PMID 24722639, 2014). "In the present study, we examined the expression patterns of MUC1 and MUC4 in non-neoplastic bladder urothelium and malignant neoplasms of bladder tissues on tissue microarrays (TMA) and tissue sections from the urinary bladder biopsies and resected samples." (PMID 24671186, 2014). "In the 108 cases, the positive expression rates (more than 5% of carcinoma cells stained) of each mucin antigen were MUC1, 47.2% (51/108); MUC2, 71.3% (77/108); MUC3, 18.5% (20/108); MUC4, 93.5% (101/108); MUC5AC, 50.0% (54/108); MUC6, 4.6% (5/108) MUC16, 16.7% (18/108) and MUC17, 86.1% (93/108)." (PMID 25551773, 2014). "MUC4 expression was significantly down-regulated in carcinoma cells compared to the non-neoplastic urothelium (mean H-score in the non-neoplastic bladder urothelium and UC being 2.54±0.21 [p<0.0001], and 0.47±0.05 respectively) (data from TMA)." (PMID 24671186, 2014). "To date, the aberrant overexpression of MUC4 has been reported in pancreatic malignancies, but not in the normal pancreas, which has made MUC4 a promising therapeutic target for anti-cancer adjuvant therapies." (PMID 19738614, 2009). "Initially, to examine the possible epigenetic regulation of MUC4 expression, we treated MUC4-negative or low-expression cancer cell lines with 5-AzadC and/or TSA." (PMID 19127263, 2009).
cancer (continued). "However, mutations of MUC4 and MUC16 are described predominantly in TET histotypes rich in cancer cells and not in thymocyte-rich tumors, suggesting the actual presence of the mutation." (PMID 37671056, 2023). "High MUC4 expression was observed in tumors from a variety of stomach sites, including fundus, corpus (body), and antrum, suggesting that metaplastic pit cells are not restricted to cancers from a specific gastric region." (PMID 37674528, 2023). "Interactions between mucin 4 (MUC4) and the epidermal growth factor receptor (EGFR) are involved in carcinogenesis, and may lead to matrix metalloproteinase-9 (MMP9) overexpression, exacerbating cancer cell invasiveness." (PMID 36400876, 2022). "In fact, like other cancer-associated mucins, MUC4 not only is overexpressed in PDAC but also displays aberrant glycosylation patterns which is absent in healthy tissues, making it a potential target for cancer vaccines 42,119." (PMID 34522225, 2021). "Notably, our data provide evidence for MUC4/Y upregulates ITGB8 downstream of the actin cytoskeleton pathway (ITGB8-FAK-Cas/CrkII/DOCK180 complex-RAC- IRSp53- WAVE2-Arp2/3-F-Actin/PFN complex) to affect actin dynamics and cancer cell motility." (PMID 25367394, 2014). "However, the direct interaction between human MUC4 and ErbB2 has not been proven at this time, moreover, studies on their role in regulating the biological properties of cancer cells have always been carried out separately in different cellular models." (PMID 22393391, 2012). "However, MUC4 contributions to pan-cancer have not been well studied." (PMID 38156143, 2023). "Moreover, 99mTc-MIRC208 and 99mTc-MIRC213 accumulated similarly in the MUC4-negative cancer cells." (PMID 35910795, 2022). "However, the contributions of MUC4 to pan-cancer have not been well characterized." (PMID 34336844, 2021). "In summary, except for CDKN2A, which is a clear outlier in the dataset under consideration, the changes in the local number of CNVs did not appear to be connected to the pan-cancer genes located in these regions (CAMTA1 and MTOR, MUC4 and TFRC, and NCOR2)." (PMID 31783642, 2019). "Given the importance of the microenvironment in cancer pathogenesis, we developed a pancreatic orthotopic model to observe metastasis using PANC-1–derived clones with or without MUC4/Y overexpression." (PMID 25367394, 2014). "However, where an association has been made between increased MUC1 expression and advanced cancer with LN metastases in studies on OSqCc, the same does not hold true according to the current evidence of MUC1 and MUC4 in OAc." (PMID 37958425, 2023).